ZSCAN16 (zinc finger and SCAN domain containing 16)
Description:
May be involved in transcriptional regulation.
Synonyms: ZNF392; ZNF435; FLJ22191; dJ265C24.3
Tractability: PROTAC: ubiquitination databases record sites on it.
Gene: Protein-coding gene on chromosome 6 (28,107,689 to 28,130,082, forward strand). Ensembl gene ENSG00000196812.
Subcellular location: Nucleus
Subcellular location (Human Protein Atlas): Nucleoplasm
Gene Ontology:
Molecular function: protein binding; sequence-specific double-stranded DNA binding; DNA-binding transcription factor activity, RNA polymerase II-specific; RNA polymerase II cis-regulatory region sequence-specific DNA binding
Biological process: regulation of transcription by RNA polymerase II
Cellular component: nucleus
Genetic constraint (gnomAD): Loss-of-function variants: 17 observed, 18.89 expected, observed/expected ratio (o/e) 0.9, 90% interval 0.62 to 1.35. The upper end of that interval is the gene's LOEUF score, 1.35, which puts it in group 5 of 6, group 1 being the genes least tolerant of losing a copy. Missense variants: 327 observed, 421.8 expected, observed/expected ratio (o/e) 0.78, 90% interval 0.71 to 0.85. Synonymous variants: 138 observed, 150.52 expected, observed/expected ratio (o/e) 0.92, 90% interval 0.8 to 1.06.
Homologues: Orthologues: chimpanzee ZSCAN16 (99% identical), macaque ZSCAN16 (98% identical), pig ZSCAN16 (86% identical), dog ZSCAN16 (83% identical), rabbit ZSCAN16 (81% identical). Paralogues in human: ZKSCAN3 (51% identical), ZNF397 (49% identical), ZKSCAN4 (49% identical), ZSCAN23 (49% identical), ZSCAN9 (48% identical), ZKSCAN1 (47% identical), ZNF24 (47% identical), ZSCAN21 (47% identical), ZSCAN31 (47% identical), ZKSCAN8 (46% identical), ZNF165 (45% identical), ZSCAN30 (45% identical), and 18 more.
Diseases named in the same sentence as ZSCAN16 in open-access papers:
ZSCAN16 is named in the same sentence as 5 diseases in open-access papers, as found by Europe PMC text mining. Sharing a sentence is not in itself a finding about the gene and the disease. The quoted sentences say what the papers report.
depression (1 paper, 2023). "Notably, TCF4, NKAPL, ZKSCAN3, ZSCAN16, ZSCAN31 have been associated with depression in previous GWASs." (PMID 36750733, 2023).
cancer (1 paper, 2022). A tumor composed of atypical neoplastic, often pleomorphic cells that invade other tissues. "MAGEC3 also upregulates a stress-related gene, WRNIP1, a DNA replication gene, MCM7, and cancer-related genes, XPO5 and ZSCAN16." (PMID 35158998, 2022).
infection (1 paper, 2012). The state of being infected such as from the introduction of a foreign agent such as serum, vaccine, antigenic substance or organism. "Genes in regions associated with control of infection included a zinc finger cluster (ZNF192, ZSCAN16, ZNF389, and ZNF165; P = 0.001), C19orf42/TMEM38A (P = 0.047), and DLGAP1 (P = 0.092)." (PMID 23082221, 2012).
Tumor (1 paper, 2025). "Tumor specimens exhibited elevated expression of DTX2, SALL1, ZNF93, ZNF146 and ZSCAN16, contrasting with reduced levels of EGR2, GATA2, and ZEB2." (PMID 40647501, 2025).
ZSCAN16 also shares sentences with these, for which no sentence is quoted: bladder cancer (1 paper).